FOXA1 (forkhead box A1)
Diseases named in the same sentence as FOXA1 in open-access papers (continued):
Sharing a sentence is not in itself a finding about the gene and the disease.
prostate carcinoma (continued). "To further confirm our results, we investigated known AR signaling genes more closely and as well as genes encoding for proteins that are most commonly associated with AR biology in prostate cancer (FOXA1, AR, and HOXB13), and found them virtually identical across all samples." (PMID 33576154, 2021). "Taken together, FOXA1 is a recurrently mutated gene across various stages of prostate cancer." (PMID 32946061, 2021). "Recent findings have shown the differential prevalence of FOXA1 mutations across prostate cancer stages, for instance the early emergence of Forkhead Wing2 coding mutations in localized disease and the enrichment of truncation mutations and SVs in metastatic diseases." (PMID 32946061, 2021). "FOXA1 mutants may contribute to specific stages of prostate cancer progression given their divergent activities due to mutations." (PMID 32946061, 2021). "In addition, we showed colocalization of HOXC4 and HOXC6 at HOXB13 sites that are also bound by FOXA1 and AR, which have been previously linked to regulation of prostate cancer cell proliferation." (PMID 32012197, 2020). "Furthermore, FOXA1 is mutated in 3–5% of prostate cancers and in subsets of cancers that exhibit the amplification of the genomic region encompassing the FOXA1 gene." (PMID 32235312, 2020). "Interestingly, FOXA1 DNA amplification was only observed in metastatic prostate cancer samples, which was associated with increased proliferation and tumor size." (PMID 30819139, 2019). "Loss of FoxA1 promotes prostate cancer progression to neuroendocrine small-cell prostate cancer." (PMID 31552182, 2019). "FOXA1 is a critical interacting partner of the nuclear hormone receptors, estrogen receptor (ERα) and androgen receptor (AR), which are associated with hormone-regulated cancers such as breast and prostate cancer." (PMID 30819139, 2019). "FoxA1 mutations occur frequently in primary and metastatic prostate cancers and may contribute to prostate tumorigenesis and cancer progression." (PMID 31552182, 2019). "Interestingly, due to its distinct roles in estrogen and androgen pathways, FOXA1 upregulation is associated with either a good prognosis or poor prognosis in breast cancer patients and prostate cancer patients, respectively." (PMID 30360388, 2018). "However, although FOXA1 forkhead domain mutations contribute to prostate cancer pathogenesis, the indel mutations we identified within the 3′-UTR and C-terminus appear to be passenger events." (PMID 30272002, 2018). "These FOXA1 mutations in 3’ untranslated region may prove useful as diagnostic markers for prostate cancer." (PMID 30272002, 2018). "Importantly, FOXA1 and POU2F1 (also known as OCT1) are also known to cooperate with GATA2 and AR in the expression of androgen-regulated genes and FOXA1 is frequently mutated in advanced prostate cancer patients." (PMID 28038451, 2017). "Therefore, in this study we evaluated the association of immunohistochemical staining levels of FOXA1 in primary prostate cancer tumor samples with risk of BCR after SRT." (PMID 26986977, 2016). "High FOXA1 expression is correlated with good prognosis in ER positive breast cancer but in prostate cancer FOXA1 level has been associated with either good or bad prognosis depending on the patient group, and has been proposed as a context dependent marker for survival in hormone dependent cancers." (PMID 24849812, 2014). "Reliance upon ligands for nuclear receptor activation could be a fundamental difference between breast and prostate cancer and may explain why the two hormone receptors respond differently to gain and loss of FOXA1." (PMID 23420418, 2013). "Loss of FOXA1 expression by targeted siRNA transfection in breast and prostate cancer cell lines results in reduction of growth suggesting an essential role in the proliferation of both cancers yet the mechanistic role for FOXA1 in ER and AR biology appears to be different." (PMID 23420418, 2013).
prostate carcinoma (continued). "Collectively, these findings suggest that SEMA3C may be a putative driver of the cancer-promoting activities associated with FOXA1 variants, implying that the FOXA1 alterations commonly observed in clinical prostate cancer samples might mediate their oncogenic effects via SEMA3C." (PMID 38528115, 2024). "Interestingly, the frequency of FOXA1 mutation varies with ethnic background, with a striking finding of FOXA1 mutations in 41% of localized prostate tumors within the Chinese Prostate Cancer Genome and Epigenome Atlas (CPGEA), which is significantly higher than western cohorts." (PMID 37958805, 2023). "In conclusion, we suggested that FOXA1 mutations may also be useful as a predictive biomarker for response to certain therapies, highlighting the potential importance of precision medicine in the treatment of prostate cancer." (PMID 37958805, 2023). "As prostate cancer progresses, the regions co-enriched with SEs and FOXA1 expand, suggesting dynamic SE remodeling." (PMID 41330917, 2025). "Our findings establish oxygen-dependent FOXA1 degradation as a linchpin connecting microenvironmental stress to transcriptional plasticity in advanced prostate cancer, offering new therapeutic avenues." (PMID 40643528, 2025). "Among 5,014 prostate cancer cases, class 1B FOXA1 alterations were the most prevalent, whereas the pathognomonic class 2 (R219) alterations were the rarest (but enriched in NEPC samples)." (PMID 39745364, 2025). "After iBET-151 treatment, H3K27ac signals associated with FOXA1 were markedly reduced in both PC-3 and DU145 cells, supporting FOXA1 as a direct SE target in prostate cancer progression." (PMID 41330917, 2025). "We replicated these findings in a second cohort of 48 primary prostate cancer tumors profiled via ChIP-seq for H3K27ac, H3K4me2, H3K4me3, FOXA1, and HOXB13." (PMID 39945744, 2025). "In prostate cancer, FOXA1’s interaction with the androgen receptor (AR) enhances AR-mediated transcription, potentially driving tumor progression and castration resistance." (PMID 40623983, 2025). "The decrease in FOXA1 hydroxylation under hypoxia provides a mechanistic basis for its destabilization and supports a broader role for PHD1 in regulating FOXA1 function and prostate cancer transcriptional programs in response to oxygen availability." (PMID 40643528, 2025). "More importantly, it provides a clinical foundation for targeting FOXA1 to enhance drug efficacy in prostate cancer patients." (PMID 39858458, 2025). "In-frame indels are a common type of cancer mutations affecting FOXA1, and F254E255 is one of the most frequent variants affecting prostate cancer patients." (PMID 39633177, 2025). "After prostate cancer, 6.7%, 5.0%, and 4.6% of breast, bladder, and salivary cancers harbored FOXA1 alterations." (PMID 39745364, 2025). "In prostate cancer, FOXA1 co-occupies reprogrammed AR-binding sites and represses an intragenic enhancer within the HIF1A locus, implicating it in the modulation of hypoxic responses." (PMID 40643528, 2025). "FOXA1 functions both as a transcriptional regulatory factor and a driver activated by SEs, playing diverse roles in prostate cancer." (PMID 41330917, 2025). "Altogether, our findings uncover a regulatory axis whereby HIF1α negatively regulates FOXA1 protein stability in prostate cancer cells, thereby suppressing androgen receptor signaling and promoting hypoxia-responsive transcriptional programs." (PMID 40643528, 2025). "The availability of a prostate organoid model with enhanced luminal identity, and the identification of Foxa1 as a major target of RA signaling led us to explore its role in prostate cancer." (PMID 39633177, 2025).
prostate carcinoma (continued). "This study identifies FOXA1-SEs as key regulators of disulfidoptosis and offers new therapeutic insight into metabolic intervention strategies in prostate cancer." (PMID 41330917, 2025). "This interplay between oxygen sensing and lineage-specific transcription factors highlights the HIF1α-FOXA1 axis as a critical node in the transcriptional reprogramming of prostate cancer cells under hypoxic stress." (PMID 40643528, 2025). "Here, we evaluated four ChIP-seq normalization methods utilizing triplicate Foxa1 ChIP-seq data performed in prostate cancer tissues from three mice." (PMID 41657940, 2025). "FOXA1 is altered in 10–40% of prostate cancers, yet its oncogenic mechanisms remain uncharacterized in vivo." (PMID 40570057, 2025). "Together, these findings reveal a FOXA1–SE–SLC7A11 regulatory axis that connects transcriptional control with redox-dependent cell death in prostate cancer." (PMID 41330917, 2025). "Collectively, these findings demonstrate that deletion of FOXA1-SEs significantly inhibits SLC7A11-induced disulfidoptosis in prostate cancer cells." (PMID 41330917, 2025). "FOXA1 is crucial for regulating the expression of numerous genes, particularly AR, during prostate cancer development and progression." (PMID 40356745, 2025). "Around 10% to 15% of prostate cancers harbor recurrent aberrations in the Forkhead Box A1 gene, FOXA1, whereby the alteration type and the effect on the forkhead (FKH) domain affect protein function." (PMID 39745364, 2025). "This study provides a novel mechanism by which prostate cancers undermine drug efficacy through the downregulation of SLC22A3 by FOXA1 competition with AR to bind to SNP rs9364554." (PMID 39858458, 2025). "We show that NKX3.1 is co-expressed and interacts with AR and FOXA1 in AR-positive prostate cancer cells, both sensitive and resistant to the AR antagonist enzalutamide." (PMID 39858088, 2025). "In prostate cancer, for instance, FOXA1 functions as a cofactor for the androgen receptor (AR), co-localizing at enhancers to coordinate hormone-regulated networks and promote cancer cell proliferation proliferation." (PMID 40032852, 2025). "From these findings, the roles of RARγ and FOXA1 in prostate cancer deserve close attention by means of orthotopic transplantation of normal and tumour organoids." (PMID 40362593, 2025). "The pioneer TF FOXA1 and GATA2 have been previously linked to the regulation of ABCC4 expression in prostate cancer, where MRP4 has been validated as a clinically relevant prognostic marker associated with metastasis." (PMID 39114357, 2024). "Parolia et al20 identified three structural classes of FOXA1 alterations in a cohort of patients with advanced prostate cancer and then used TCGA data to confirm the classifications." (PMID 39536277, 2024). "We detected that the replacement of AR by GR in enzalutamide-exposed prostate cancer cells occurs almost exclusively at pre-accessible chromatin sites displaying FOXA1 occupancy." (PMID 38015476, 2024). "FOXA1 has similar expression in all Gleason grades of prostate carcinomas while FOXA2 has been found in some prostate cancer with high Gleason scores and in neuroendocrine small cell carcinomas." (PMID 39470735, 2024). "Our results indicate that alterations to FOXA1 lead to increased SEMA3C expression levels in prostate cancer specimens and also in vitro." (PMID 38528115, 2024). "We next examined three key prostate cancer oncogenes known to have regional enhancer interactions: FOXA1, MYC and AR4,5,45–49." (PMID 39020220, 2024). "GIGGLE analysis revealed a significant overlap between H3K27ac lost sites and the cistromes of key transcriptional and epigenetic regulators of prostate cancer, including AR, FOXA1 and HOXB13, supporting their functional relevance." (PMID 39117800, 2024).
prostate carcinoma (continued). "Overall, we identified chromatin pre-accessibility and FOXA1-mediated repression as important regulators of GR action in prostate cancer, pointing out new avenues to oppose steroid receptor-mediated antiandrogen resistance." (PMID 38015476, 2024). "We then stratified prostate cancer into FOXA1 high-expression and low-expression groups using a cut-off of 7.5." (PMID 39097593, 2024). "This study uncovers a novel regulatory mechanism of the FOXA1/PUS1/EIF3b signaling axis in prostate cancer bone metastasis." (PMID 39247811, 2024). "For initiation and early progression of primary prostate cancer, several driver mutations or alterations have been described e.g., inactivating SPOP mutations, activating FOXA1 mutations, TMPRRS-ERG fusion, loss of PTEN or AR alterations." (PMID 38704600, 2024). "Nevertheless, the predominant impact of A485 on FOXA1 chromatin binding warrants further validation in other prostate cancer cell lines in future studies." (PMID 38564048, 2024). "Work presented here outlines one avenue of SEMA3C regulation and is intended to inspire future work which will be needed to fully understand the mechanisms governing elevated SEMA3C levels in prostate cancer patients containing FOXA1 alterations." (PMID 38528115, 2024). "It has been reported that KDM1A can be involved in prostate cancer by increasing chromatin accessibility of the FOXA1 promoter." (PMID 38295985, 2024). "FOXA1 is crucial for the chromatin binding of the androgen receptor (AR) in both normal prostate epithelial cells and the luminal subtype of prostate cancer (PCa)." (PMID 38851846, 2024). "Prostate cancers driven by androgen receptor (AR) or FOXA1 are more sensitive to SWI/SNF degraders than cancers in which subunits of the SWI/SNF complex are mutated." (PMID 39697230, 2024). "Our findings reveal that FOXA1 alterations lead to elevated levels of SEMA3C both in prostate cancer specimens and in vitro." (PMID 38528115, 2024). "In prostate cancer, FOXA1 is known to have AR-dependent and AR-independent activities; moreover, in those that are AR-dependent, FOXA1 can exert both positive and negative effects on expression of AR-regulated genes." (PMID 38528115, 2024). "This proposal is supported by the previous observation that JQ1 can promote prostate cancer invasion independently of BET proteins by directly inhibiting the FOXA1 transcription factor." (PMID 38084912, 2024). "5hmC-sequencing in cfDNA identified a subgroup of prostate cancer patients with preexisting activation (5hmC hypermethylation) of gene sets involving AR, FOXA1 and GRHL2 before initiating ADT." (PMID 37904926, 2024). "Many genes under these cancer-intrinsic and extrinsic pathways were downregulated in the FOXA1 mutant group compared to the control group, suggesting the limitation of the FOXA1 function as a transcription factor in FOXA1 mutant prostate cancer." (PMID 37958805, 2023). "FOXA1 acts as a pioneer factor in prostate cancer and governs expression of cell cycle regulatory genes in prostate cancer." (PMID 37868033, 2023). "Most of these genes were highly expressed in the control group compared to FOXA1 mutant prostate cancer." (PMID 37958805, 2023). "As a result of our in silico research, we identified novel therapeutic targets and potential drug candidates for FOXA1 mutant prostate cancer." (PMID 37958805, 2023). "Despite the widely accepted recognition of the importance of tumor microenvironment, comprehensive investigation into specific aspects such as immune-related signaling in FOXA1 mutant prostate cancer has remained largely unexplored." (PMID 37958805, 2023).
prostate carcinoma (continued). "We input FOXA1 and the 168 upregulated DEGs to identify physical protein interactions among the overexpressed genes in FOXA1 mutant prostate cancer via the PPI analysis tool STRING." (PMID 37958805, 2023). "This notion was further supported by the downregulation of tumor suppressor genes within FOXA1 mutant prostate cancer." (PMID 37958805, 2023). "As an example, upon comparing signaling as functions of prostate cancer development, it was clear that some gene networks are consistently similar (i.e. AR and FOXA1) whereas others are highly dependent on the ecosystem (i.e. MYC)." (PMID 37059746, 2023). "In this research, we investigated the cellular and molecular characteristics of FOXA1 mutant prostate cancer using the TCGA dataset." (PMID 37958805, 2023). "As a result, 58 cancer genes were upregulated and 436 cancer genes were downregulated in FOXA1 mutant prostate cancer." (PMID 37958805, 2023). "Our analysis revealed that B cells are significantly enriched in the control group compared to FOXA1 mutant prostate cancer, and this result was further confirmed by GSEA analysis." (PMID 37958805, 2023). "In Chinese populations, FOXA1 mutations were the prominent alteration, while ETS fusion was regarded as the signature of prostate cancer in western cohorts." (PMID 37726835, 2023). "By identifying patients with FOXA1 mutations and tailoring their characteristics accordingly, we investigated which genes and pathways altered and how immune landscapes changed in FOXA1 mutant prostate cancer." (PMID 37958805, 2023). "B cells were significantly highly present in the control group compared to FOXA1 mutant prostate cancer using TIMER." (PMID 37958805, 2023). "In this study, we aimed to unravel the intricate molecular characteristics of FOXA1 mutant prostate cancer through comprehensive in silico analysis of transcriptomic data from The Cancer Genome Atlas (TCGA)." (PMID 37958805, 2023). "Although the oncogenic functions of FOXA1 have been extensively studied in breast and prostate cancer, its potential role in regulating cancer-specific transcriptional programs in other tumor lineages is just beginning to be appreciated." (PMID 37691854, 2023). "FOXA1 (Forkhead box A1) is known to be essential for the survival of normal prostate and prostate cancer tissue by maintaining AR signaling." (PMID 36711033, 2023). "AR-co-factors (e.g., FOXA1 and HOXB13) bring about H3K4me3/H3K27me3 bivalent marks at neural lineage–associated genes in Myc-driven advanced prostate cancer." (PMID 37876590, 2023). "Given the cooperativity between FOXA1 and nuclear receptors in breast and prostate cancers, it was notable that the related nuclear receptor, GR, was the top ranked TF among the FOXA1 interactomes in FOXA1-dependent NSCLC." (PMID 37691854, 2023). "FOXA1 is necessary for the viability of breast and prostate cancer cells; however, its role in other cancers is unclear." (PMID 37691854, 2023). "In other words, FOXA1 is an oncogene in prostate cancer, whereas in EC, the evidence has suggested that FOXA2 is a tumor suppressor." (PMID 35703180, 2022). "These CREs were preferentially bound by other key prostate cancer transcription factors, including FOXA1 and the AR." (PMID 36212399, 2022). "Dysregulation of alternative splicing in prostate cancer is linked to transcriptional programs activated by AR, ERG, FOXA1, and MYC." (PMID 36170835, 2022). "A recent study found that FOXA1 overexpression suppresses interferon signaling and promotes cancer immuno- and chemotherapy resistance in prostate cancer and bladder cancer." (PMID 35974000, 2022).